CDA (cytidine deaminase)
Diseases named in the same sentence as CDA in open-access papers (continued):
Sharing a sentence is not in itself a finding about the gene and the disease.
small cell lung carcinoma (1 paper, 2022). Small cell lung cancer (SCLC) is a highly aggressive malignant neoplasm, accounting for 10-15% of lung cancer cases, characterized byrapid growth, and early metastasis. "Most small cell lung carcinoma (SCLC) cell lines also express low levels of CDA mRNA and as shown for NCIH69 and NCIH82 cells, this agrees with the absence of CDA protein detection." (PMID 36424385, 2022).
triple-negative breast carcinoma (1 paper, 2024). An invasive breast carcinoma which is negative for expression of estrogen receptor (ER), progesterone receptor (PR), and human epidermal growth factor receptor 2 (HER2). "Gemcitabine, a chemotherapeutic treatment for pancreatic, bladder and metastatic triple-negative breast cancers, can be transported into the cytoplasm of Gammaproteobacteria (class) using nucleoside transporter (NupC), where it gets inactivated by bacterial cytidine deaminase." (PMID 38713383, 2024).
Wilson disease (1 paper, 2022). A very rare inherited multisystemic disease presenting non-specific neurological, hepatic, psychiatric or osseo-muscular manifestations due to excessive copper deposition in the body. "Significantly raised levels of cdA and cdG in both the R and S isoforms were also found in the brain tissues of the Long-Evans Cinnamon (LEA) rat, an animal model for human Wilson’s disease, and the Long-Evans Agouti rat (LEC), healthy rats, using NanoLC-NSI-MS/MS analysis." (PMID 36008969, 2022).
xeroderma pigmentosum (1 paper, 2020). Xeroderma pigmentosum (XP) is a rare genodermatosis characterized by extreme sensitivity to ultraviolet (UV)-induced changes in the skin and eyes, and multiple skin cancers. "In agreement with this, cdG and cdA adducts accumulate in DNA of keratinocytes from NER-deficient xeroderma pigmentosum (XP) complementation group C (XPC) and CSA patients exposed to X-rays and potassium bromate (KBrO3), as well as in organs of CSB−/− knockout mice." (PMID 33553154, 2020).
tumor (115 papers, 2003 to 2026). "CDA reduction in cancer cells makes tumors more sensitive to immunotherapy, presumably by overcoming immunosuppressive tumor-associated macrophages (TAMs) and forcing them to adopt an immunostimulatory phenotype." (PMID 40011298, 2025). "In PDA, the loss of all circulating antibodies as well as the loss of the activation‐induced cytidine deaminase, which allows the isotype switch of antibodies, similarly accelerated tumour progression." (PMID 40831074, 2025). "CDA expression corresponded with either the CD206+ immunosuppressive percentage or tumor border and center CD68+ tumor–associated macrophage infiltration in two homogeneous categories of PDAC patients." (PMID 40011298, 2025). "We found that X55 inhibited the growth of 40% of CDA-deficient tumor cell lines (8 of 20) and 22% of CDA-proficient tumor cell lines (2 of 9), without affecting the growth of non-tumor cell lines, regardless of CDA expression status." (PMID 35925417, 2022). "We screened the CNRS-Institut Curie chemical library (8560 compounds) to identify new anticancer drugs specifically targeting CDA deficiency versus proficiency in tumor cells." (PMID 35925417, 2022). "In this study, we aimed to develop a new anticancer treatment specifically inhibiting the growth of CDA-deficient tumor cells." (PMID 35925417, 2022). "We identified a naphthol derivative, X55, as a new potential anticancer molecule that preferentially targets CDA-deficient tumor cells." (PMID 35925417, 2022). "We therefore investigated the metabolic pathways altered by CDA depletion and the reasons for which X55 preferentially targeted CDA-deficient tumor cells." (PMID 35925417, 2022). "The association between CDA expression and the sensitivity/resistance of tumor cells to treatment with gemcitabine is well described." (PMID 34777634, 2021). "Treatment with CDA was associated with the reduction in expression of HCL tumour markers (CD20, CD11c) and increased expression of myeloid markers (CD14, CD68, CD66b, ARG1)." (PMID 34561502, 2021). "Of the clinicopathological factors, only tumor stage correlated with CDA, although this association was weak." (PMID 34830914, 2021). "The human APOBEC3A (A3A) cytidine deaminase is a powerful DNA mutator enzyme recognized as a major source of somatic mutations in tumor cell genomes." (PMID 34403699, 2021). "For anti-tumor drugs, loss of CDA expression seems to act as a new predictive marker of cancer susceptibility." (PMID 30002603, 2018). "In our previous retrospective study of patients with advanced BTC who were treated with gemcitabine plus cisplatin, the variant rs1048977 allele in the CDA gene was associated with tumor response in a dominant model." (PMID 29113399, 2017). "In Mycoplasma hyorhinis-infected tumor cell cultures, mycoplasma-encoded cytidine deaminase (CDA) and pyrimidine nucleoside phosphorylase (PyNP) compromise the antitumor activity of nucleoside analogues such as gemcitabine and 5-FU by deamination." (PMID 28976984, 2017). "In our study, we combined clinical data and found that the CDA gene was highly expressed in age ≤ 50 group, which may be associated with early tumour development or progression." (PMID 39944833, 2025). "CDA expression is downregulated in about 60% of cancer cells and tissues, mainly by promoter DNA methylation, suggesting that CDA loss may contribute to the growth of tumor cells." (PMID 35925417, 2022). "Our study suggests that the concomitant reduction of NAMPT and PARP-1 activities in CDA-deficient tumor cells may be associated with a better prognosis." (PMID 32807821, 2020). "CDA-depleted HeLa cells have many metabolic abnormalities and are characterized by a significant decrease in the abundance of several oncometabolites for which an accumulation has been implicated in both tumor initiation and progression, and in resistance to anticancer treatments." (PMID 35925417, 2022).
tumor (continued). "Ridge plot indicated that A3C represented the most abundant cytidine deaminase among seven family members and was upregulated in tumor compared with normal tissues." (PMID 41501001, 2026). "A previous study suggested bacteria class Gammaproteobacteria (e.g., K. pneumoniae) harbored in PC tumor was able to metabolize the gemcitabine to the inactive 2’, 2’-difluorodeoxyuridine through a long isoform of the enzyme cytidine deaminase." (PMID 41409546, 2025). "A3B expression and its CDA activity were confirmed in liver cells and tumor tissues of mice overexpressing A3B." (PMID 40213992, 2025). "Most interestingly, following anti-PD-1 therapy, the survival rate of KPC FC1245 tumor–bearing mice was markedly increased by genetic suppression of CDA, confirming the theory that CDA targeting overcomes anti-PD-1 resistance." (PMID 40011298, 2025). "In untreated tissue, CD8+ T lymphocytes were absent from the tumor center, demonstrating their incapacity to infiltrate the tumor, but CDA-targeted tumors showed an increase in CD8+ T cell infiltration." (PMID 40011298, 2025). "Within PDAC tumor environments, Gammaproteobacteria can metabolize gemcitabine into the non-active form 2′, 2′-difluoro deoxyuridine through the enzymatic action of cytidine deaminase, thus reducing its efficacy against cancer." (PMID 40497987, 2025). "Regarding the combination of gemcitabine and paclitaxel, paclitaxel has been shown to increase the concentration of gemcitabine in the tumor tissue by inhibition of the enzyme cytidine deaminase leading to reduced gemcitabine elimination." (PMID 40946104, 2025). "Drugs that have been marketed, such as Cedazuridine + Decitabine, improve anti-tumor efficacy by inhibiting cytidine deaminase, but toxic reactions such as bone marrow suppression need to be closely monitored." (PMID 40564937, 2025). "Compared to resistant control (sgNT) tumors, CDA targeting in Panc02 cells led to reduced tumor growth and weight, as well as total regression after anti-PD-1 treatment." (PMID 40011298, 2025). "This increased tumor weight and mesenteric lymph node metastases to the levels seen in IgG-treated groups, suggesting that CDA re-expression restored anti-PD-1 resistance." (PMID 40011298, 2025). "Recent studies have also shown that pyrimidine nucleosides are critically involved in mediating communications between macrophages and tumor cells through engaging cytidine deaminase (CDA) and P2Y6 signaling." (PMID 40223597, 2025). "Researchers have demonstrated that cytidine deaminase (CDA) in tumor cells aids in producing and releasing uridine diphosphate (UDP) and other uracil nucleotides." (PMID 40055311, 2025). "Inhibition of this pathway—either by targeting P2Y6 in TAMs or cytidine deaminase (CDA) in tumor cells—restored cytotoxic T-cell infiltration and sensitized tumors to anti-PD-1 therapy." (PMID 40867316, 2025). "CDA targeting in PDAC cells altered the tumor microenvironment (TME), enabling T cells to respond to anti-PD-1." (PMID 40011298, 2025). "It is then converted into 5′-deoxy-fluorouracil (5′-DFUR) by cytidine deaminase (CD), which is abundant in both liver and tumor tissues." (PMID 40722718, 2025). "Gammaproteobacteria metabolize gemcitabine, inducing drug resistance via the bacterial enzyme cytidine deaminase (CDA), while CDA conversely directs 5- Fluorouracil (5-FU) to tumor cells, reducing its toxic effects and improving its pharmacokinetic properties." (PMID 39859442, 2025). "The similarity between the cellular and molecular pathways hijacked by a tumor and those involved in tissue repair raises the possibility of a physiological function of this CDA–UDP–P2Y6 axis." (PMID 38844817, 2024).
tumor (continued). "CDA targeting in Panc02 cancer cells resulted in decreased tumor growth and weight and complete regression following anti-PD-1 treatment compared to resistant control (sgNT) tumors." (PMID 38844817, 2024). "Disrupting this communication through CDA or P2Y6 inhibition leads to the infiltration of effector T cells into the tumor, transforming it into a T cell-inflamed or ‘hot’ state, a condition that enables the effectiveness of anti-PD-1 treatment." (PMID 38844817, 2024). "Re-expression of CDA re-established anti-PD-1 resistance, as suggested by the increase in tumor weight and mesenteric lymph node metastases to the levels observed in IgG-treated groups." (PMID 38844817, 2024). "In the second step, 5′-DFCR is converted to 5′-Deoxy-5-Fluorouridine (5′-DFUR) by cytidine deaminase, which is highly active in the liver and tumor tissue." (PMID 36803558, 2023). "LC-MS/MS-MRM analyses of tumor interstitial fluid dG and dC levels showed that PNPi increased dG levels while CDA expression significantly reduced dC levels." (PMID 35653193, 2022). "Bacterial CDA from E. coli displaying an efficient activity towards various tumor cells, however, CDA from yeast displayed a feasible kinetic properties for 5-FC." (PMID 36164544, 2022). "PmTriTNE synergized with CDA to transform the cold tumor into a hot tumor, eradicate the large established TNBC tumor, and induce protective immune memory in a 4T1 orthotopic tumor model without causing obvious toxicity." (PMID 36089659, 2022). "The bacteria inside the tumor express an enzyme, cytidine deaminase, which converts gemcitabine to its inactive form." (PMID 35740402, 2022). "Although median CDA expression was similar between tumor samples (n = 483, obtained from TCGA) and normal tissue samples (n = 347, obtained from GTEx), ~25% of the tumor samples overexpressed CDA compared with normal samples." (PMID 35999456, 2022). "Tumor antigens and DAMPs released from dead tumor cells then cooperate with CDA to promote DC maturation and cross‐priming, which enables tumor antigen spread and achieves in situ vaccine effects." (PMID 36089659, 2022). "Lower level of R/S cdG and cdA ratios were depicted in 17-week-old brain tissues of both control and tumor-bearing animals compared to 4-week-old tissues." (PMID 36008969, 2022). "We also performed a large-scale metabolomic study with two isogenic tumor cell lines, CDA-depleted HeLa cells and control HeLa cells expressing endogenous CDA." (PMID 35925417, 2022). "So, mediating the 5-FU to the tumor cells by CDA is one of the most feasible approaches to direct the drug to the tumor cells, reducing its toxic effects and improving their pharmacokinetic properties." (PMID 36164544, 2022). "We have demonstrated that HCL response to CDA is dependent on both depth of tumour depletion and the immune microenvironment." (PMID 34561502, 2021). "CDA expression was measured by immunohistochemistry in tumor tissues of patients before and after neoadjuvant chemotherapy." (PMID 33874986, 2021). "As would be expected, reduced expression of the B cell marker CD20 post-treatment correlated with subsequent durable clinical response (adj p = 3.17 × 10–8) as a measure of overall tumour response to CDA therapy." (PMID 34561502, 2021). "CDA was downregulated in more than half of tumor cells and tissues, and DNA damage and genomic instability are consequences of CDA silencing." (PMID 34404882, 2021). "In tumor cells, DCK inhibition causes gemcitabine resistance, while CDA suppression results in gemcitabine chemosensitivity." (PMID 34458141, 2021). "Strong expression of CDA was detected within the glandular and, to a lesser extent, the undifferentiated components of the tumor by immunohistochemistry." (PMID 31941506, 2020). "Guadecitabine, also known as SGI-110, was specifically designed to be resistant to degradation by cytidine deaminase and prolong the exposure of tumor cells to the active metabolite, decitabine." (PMID 32106810, 2020).
tumor (continued). "Strongly positive tumour epithelial cytidine deaminase (CDA) expression favoured benefit from SEQ therapy (PFS HR 0.31, 95% CI 0.13–0.70)." (PMID 32350413, 2020). "Eight patients whose tumours had strongly positive CDA expression received second-line chemotherapy on disease progression: 6 patients in the CON arm and 2 patients in the SEQ arm." (PMID 32350413, 2020). "Patients with strong tumour CDA expression had higher whole-blood CDA activity compared with patients with lower levels of staining (p = 0.031)." (PMID 32350413, 2020). "CDA high-expressing tumours are theoretically more resistant to cytidine-based therapies, including gemcitabine." (PMID 35582220, 2020). "IHC showed the enhanced expression of CDA in tumor samples after 5AC treatment in patients who were responsive to 5AC treatment." (PMID 31040918, 2019). "A3G, a cytidine deaminase extensively studied in antiviral responses, shows immune-related transcription profiles in the tumour mixture." (PMID 30624727, 2019). "It has been shown that Abraxane® increases tumor uptake of gemcitabine via inhibiting gemcitabine metabolizing enzyme (cytidine deaminase)." (PMID 30674344, 2019). "Both THP-1 and U266, which showed relatively higher expression of CDA mRNA and protein of the tumor cell lines used, are resistant to 5AC and DAC." (PMID 31040918, 2019). "Tumor xenografts were implanted in nude mice to verify the effect of CDA silencing on tumor growth in vivo." (PMID 30002603, 2018). "According to these data, lurbinectedin-induced depletion of TAMs downregulates CDA expression, which is expected to lead to an increase in gemcitabine tumor levels." (PMID 27780828, 2016). "NSCs have also been used to carry CDA and IFN-beta cDNAs together, boosting the bystander cytotoxicity with immune response against the tumor and resulting in better antitumor response compared to CDA alone." (PMID 24202446, 2013). "Our data suggests that the gemcitabine metabolising capacity of CDA was decreased in transplanted PDAC tumours during CAP treatment." (PMID 23840665, 2013). "Frese etal. demonstrated that nab-paclitaxel reduced the level of CDA expression in PDA tumours resulting in an increase of intra-tumoural GEM metabolites." (PMID 23840665, 2013). "Because of the toxicity we observed with the GEMCAP combination we quantified CDA enzyme activity in the tumour tissue." (PMID 23840665, 2013). "The present data first confirm that CDA-2 treatment directly results in a growth arrest of lung tumor and an extended life span in mice indicating the potent anti-tumor activity of CDA-2 in inhibiting tumor growth in a dose-dependent manner." (PMID 23284890, 2012). "This study directly tested the important tumor inhibitory effect of CDA-2 by using experimental lung tumor models." (PMID 23284890, 2012). "Mice survival times were assessed and showed that the life spans of tumor-bearing mice were prolonged when given different concentration of CDA-2 treatment." (PMID 23284890, 2012). "Cytidine deaminase (cda) is a critical enzyme for the activation of capecitabine in hepatocytes and tumour cells." (PMID 20179805, 2010). "On the other hand, downregulated genes in epidermal cells during malignant progression that are present in the HPV-tumor associated Signature 6 were: KLK11, CDA, CRABP2, CDA and KIF1C." (PMID 19721808, 2009). "Furthermore, according to a meta-analysis of several tumor types, anti-PD-1 resistance is mediated by CDA induction in cancer cells." (PMID 40011298, 2025). "While low CDA expression was associated with lower total and CD206+ TAMs, but higher CD8+ T cell infiltration, CDAhigh PDAC showed considerably decreased CD8+ T cell infiltration in the tumor center." (PMID 40011298, 2025). "Additionally, lessening cytidine deaminase (CDA) activity, which can obstruct gemcitabine deamination, has enhanced tumor cell sensitivity to gemcitabine." (PMID 38492776, 2024).